CD4 (CD4 molecule)
Diseases named in the same sentence as CD4 in open-access papers (continued):
Sharing a sentence is not in itself a finding about the gene and the disease.
myasthenia gravis (47 papers, 2013 to 2026). Myasthenia gravis (MG) is a rare, clinically heterogeneous, autoimmune disorder of the neuromuscular junction characterized by fatigable weakness of voluntary muscles. "Previous studies have shown that CD4+CD25+CD127low Treg cells are associated with myasthenia gravis and acute pancreatitis." (PMID 36035072, 2022). "A significant increase in the percentage of Tregs among CD4+ T cells was observed after six months of RTX treatment in refractory myasthenia gravis." (PMID 38448810, 2024). "Myasthenia gravis (MG) is an exemplary autoimmune disease that is dependent on CD4 + T cells and mediated by B cells." (PMID 37924056, 2023). "We fine mapped the CLTA4 locus in myasthenia gravis and demonstrated for the first time that causal alleles result in low expression of CTLA4 in CD4+ T‐cells." (PMID 34279044, 2021). "Orbital myositis and myasthenia gravis in human immunodeficiency virus-infected patients correlate closely with immunity status following a marked increase in CD4+ T cell counts." (PMID 33381117, 2020). "Additionally, several lncRNAs such as IFNG-AS1 have been implicated in CD4+ T cell mediated pathologies such as myasthenia gravis (MG), which offers further support for the physiological role of lncRNAs." (PMID 31336952, 2019). "As there is a loss of thymic organo-specific characteristics that induce CD4/CD8 double-positive T cells, as seen in myasthenia gravis and pure red cell aplasia, symptomatic paraneoplastic syndrome does not appear." (PMID 25013463, 2014). "Similarly, IFN-γ promoted a significant increase in the conversion of TCR-stimulated CD4+CD25− T cells to suppressive CD4+CD25+FOXP3+ T cells in patients with Guillain-Barré syndrome or myasthenia gravis." (PMID 38822334, 2024). "In addition, the conversion rate of CD4+CD25− T cells into CD4+CD25+FOXP3+ T cells was significantly higher in healthy individuals than in patients with Guillain-Barré syndrome or myasthenia gravis." (PMID 38822334, 2024). "Myasthenia gravis (MG) is a CD4+ T cell-dependent antibody-mediated autoimmune disease, which leads to destruction of the skeletal muscle nicotinic acetylcholine receptor (AChR) at the neuromuscular junction resulting in the hallmark MG symptoms of muscle weakness and fatigue." (PMID 35720339, 2022). "Current investigations have revealed that the percentage of CD4+CXCR5+Tfh to CD4+T cells in the PB of patients with myasthenia gravis is considerably greater than that of healthy controls and there is a positive correlation between the percentage and the stage of the disease." (PMID 35494526, 2022). "Interestingly, effector CD4+ T cells exist in both ends of the two directions in myasthenia gravis, while they primarily exist in one direction after the effector memory CD4+ T cells or Treg stage and have more branches in HCs." (PMID 34521820, 2021). "Myasthenia gravis (MG) is an antibody-mediated disease with T-cell-driven immune pathogenesis and complex interactions between CD4+ T cells and B cells characterized by fatigable muscle weakness of the ocular, facial, bulbar, respiratory, and limb muscles." (PMID 37781409, 2023). "The third is the role of CD4+ T cell subtypes and cytokines in MG and experimental autoimmune myasthenia gravis (EAMG)." (PMID 35458209, 2022). "Myasthenia gravis (MG) is a CD4+ T-cell-dependent HAID, where autoantibodies interfere with neuromuscular transmission, causing muscle weakness." (PMID 33537838, 2021). "The importance of CD4+ T cells in the pathogenesis of MG is consistent with previous data on experimental autoimmune myasthenia gravis (EAMG) and human MG." (PMID 33061827, 2020). "A side-by-side comparison between the dendritic cell (DC):TC co-culture system and conventional peripheral blood mononuclear cell (PBMC) cultures for detection of hAChR-peptide-responsive CD4+ T cells in myasthenia gravis (MG) patients." (PMID 29114250, 2017).
myasthenia gravis (continued). "Three patients had chronic pulmonary conditions, 2 had decompensated liver cirrhosis, 1 had myasthenia gravis, and 1 had newly diagnosed HIV and presented with AIDS-defining illness (CD4 count, 0 cells/mm3)." (PMID 39494451, 2024). "Increasing evidence of CD68+ staining in myositis has been reported in studies showing that both CD4+/CD8+ and CD68+ macrophages are present in muscle biopsy specimens from patients with ICI-induced myositis and myasthenia gravis." (PMID 36358686, 2022). "Another study presents that lncRNA IFNG-AS1 promotes CD4+ T cell activation and Th1/Treg cell proliferation via regulating HLA-DRB1 in myasthenia gravis." (PMID 32547537, 2020). "Myasthenia gravis symptoms subsequently worsened over several months, and 12 months after ART initiation, a lower dose of azathioprine was reinitiated (CD4+ ~250 cells/mm3), resulting in symptomatic improvement." (PMID 32973647, 2020). "The experimental results showed that in the animal model of MG (experimental autoimmune myasthenia gravis, EAMG), the number of CD4+CD25+ Tregs in CD4+ T spleen cells decreased and the expression of FoxP3 at mRNA level also decreased correspondingly." (PMID 26347149, 2015). "In myasthenia gravis (MG) patients, the dysfunction of CD4+CD25+ regulatory T cells (CD4+CD25+ Tregs) may be one of the important pathogenesis of MG." (PMID 26347149, 2015). "The pathogenesis of MG is relevant to CD4 + T cells, thus in the current study, we expected to investigate whether AS-IV ameliorates experimental autoimmune myasthenia gravis (EAMG) symptoms and affects EAMG by modulating the subsets of CD4 + T cells." (PMID 37542273, 2023). "Moreover, studies using the murine experimental autoimmune myasthenia gravis (EAMG) model suggest that CD4 and not CD8 T cells are instrumental in the pathogenesis of MG." (PMID 40525756, 2025).
renal cell carcinoma (47 papers, 2000 to 2026). "Among these, EGFR and CD4 exhibited a protective role in renal cell carcinoma, whereas TRIB3 and ZAP70 were identified as risk factors (P - value <0.05)." (PMID 40104395, 2025). "The findings of the present and previous studies would suggest that a conspicuous tumour T-lymphocyte infiltrate, in particular CD4+, was associated with poor cancer survival in patients with renal cell cancer." (PMID 14612901, 2003). "In patients with renal cell carcinoma (RCC), CD4 expression is significantly elevated and closely linked to prognosis." (PMID 40104395, 2025). "The presence of CD4+ T lymphocytes infiltrating tumors has been linked to a reduced likelihood of relapse-free survival in translocation renal cell carcinoma (RCC)." (PMID 38730579, 2024). "The CD4+/CD8+ ratio of renal cell carcinoma patients treated with vinblastine in combination with human IFN-α was higher compared to those that had been treated with vinblastine alone." (PMID 35158547, 2022). "Increasing evidence has revealed that renal cell carcinoma displays large expansion of double positive CD4+ CD8+ T Cells with expression of exhaustion markers." (PMID 36575439, 2022). "In support of this idea, TAMs isolated from human renal cell carcinoma were previously able to induce CTLA4 expression in CD4+ T cells." (PMID 35418199, 2022). "Tumor recurrence of renal cell carcinoma can be prevented by the memory immune effect of CD4 T cells." (PMID 33714943, 2021). "Additionally, scientific evidence supports the utilization of CD4/8 cells as an immunotherapeutic strategy for renal cell carcinoma (RCC)." (PMID 38594655, 2024). "Similar proportions of CD4+ T cells have been reported in TILs derived from renal cell carcinoma specimens, and suggest that CD4+ cells may too have a functional role." (PMID 30039427, 2018). "In renal cell carcinoma (RCC), tumor-infiltrating CD4+ T cells were found to predominantly express both CCR5 and CXCR3, supporting a Th1-polarized immune infiltrate." (PMID 40475782, 2025). "In renal cell carcinoma, UBE2C is strongly correlated with the infiltration of various immune cells, including M0 macrophages, regulatory T cells, and CD4+ memory T cells in RCC." (PMID 38577722, 2024). "The presence of CD4+ T lymphocytes infiltrating tumors has been correlated with unfavorable relapse-free survival outcomes in cases with translocation renal cell carcinoma (RCC)." (PMID 38730579, 2024). "Renal cell carcinomas are characterized by abundant leukocyte infiltration, including CD8+ T cells, CD4+ T cells and natural killer (NK) cells, as well as myeloid cells with characteristics of macrophages and neutrophils." (PMID 37047824, 2023). "who reported an increase of LAG-3+ and TIM-3+ CD4+ and CD8+ T cells in an in-vitro PD-1 ICB assay in renal cell carcinoma TILs." (PMID 35874702, 2022). "In the renal cell carcinoma case, “small nests” of tumors showed a higher density of CD8A, CD8B, and CD4 expression than “large nests,” and these transcript levels were even higher in regions of desmoplasia surrounding vessels." (PMID 35584630, 2022). "Research on patients with renal cell carcinoma (RCC) found that blocking the TIM-3 pathway could inhibit the activation of the TIM-3 pathway to restore the proliferation of CD4+ and CD8+ TILs and increase the production of IFN-γ." (PMID 34743730, 2021). "Since TIM-3, which binds to CEACAM1, are expressed in immune cells such as CD4+ and CD8+ T lymphocytes, CEACAM1 may play an important role in mediating immune cell infiltration in renal cell carcinoma." (PMID 36712923, 2023). "In A clinical study of 22 patients with renal cell carcinoma before and 3 months after cryoablation and blood samples of some patients, it was found that CD8+T, CD4+T, granzyme A(GZMA), CD11c transcription levels were significantly increased, and CD8/FOXP3 was increased after cryoablation." (PMID 36761748, 2023).
renal cell carcinoma (continued). "This study shows the importance of CD4+ and CD8+ T cells in vaccinia virus-mediated oncolytic virotherapy and suggests that this approach may be evaluated for the treatment of human renal cell carcinoma." (PMID 27057460, 2016). "In renal cell carcinoma (RCC) patients, IFN-DC were described to promote significantly higher numbers of autologous cytotoxic antitumor responses in vitro, as compared to classic DC, as well as to reduce regulatory-type T cells (Tregs) among CD4+ T-cell responder populations." (PMID 33086492, 2020).
thyroid cancer (47 papers, 2013 to 2025). "But the cumulative survival curves showed that the infiltration of B cell, CD8 + T cell, CD4 + T cell, macrophage, neutrophil and dendritic cell didn’t cause a significant change in survival time of thyroid cancer patients." (PMID 37208644, 2023). "Signal transducer and activator of transcription 6 (STAT6) is significantly positively associated with immune infiltration of B cells, CD4 T cells, neutrophils, macrophages and dendritic cells of thyroid cancer." (PMID 35185791, 2022). "Aggressive follicular cell-derived thyroid cancer either at presentation or during follow-up is associated with down-regulation of the T cell populations specifically CD4+ T cells, gamma-delta T cells, and NK T-like cells but up-regulation of MDSCs and altered memory T cells." (PMID 38235146, 2023). "Male gender was a protective factor for TDs development, especially for hypothyroidism (p < 0.001); age emerged as a variable associated with both hypothyroidism (p = 0.03) and thyroid cancer (p = 0.03), while CD4+ cell nadir <200 cell/mm3 was associated with symptomatic hyperthyroidism (p = 0.005)." (PMID 31857648, 2019). "In thyroid cancer, immune cells (especially neutrophils, dendritic cells, B cells, CD4+ T cells, and macrophages) were also positively correlated with CTHRC1 expression, while Th17 cell infiltration was negatively correlated with CTHRC1 expression." (PMID 39052013, 2024). "The combination of PD-1 on the T cells and PD-1 on the thyroid cancer cells not only inhibits the proliferation of CD4+ T cells but also induces the apoptosis of CTLs, which plays an important role in the uncontrolled proliferation of cancer cells." (PMID 35935973, 2022). "Additionally, PANoptosis participates in thyroid cancer immune evasion by modulating macrophages, CD4+T cells, activated T cells, B cells, and TNF signaling pathways." (PMID 41430255, 2025). "For example, approaches that enhance CD4 + T cell activity may introduce new strategies to improve the immune response in patients with thyroid cancer." (PMID 40785195, 2025). "Our study suggests that PANoptosis may be involved in immune dysregulation in thyroid cancer by regulating macrophages, CD4+ T cells and activated T and B cells and TNF signalling pathways." (PMID 39104814, 2024). "Finally in thyroid cancer, epithelial cells are upregulated, and B cells, CD4 T cells, CD8 T cells, cDCs, and NK cells are downregulated." (PMID 39120585, 2024). "Tregs (CD4+CD25hiCD127lo) inhibit the anti-tumor response by producing IL-10 and expressing immune checkpoints CTLA-4 and PD-1, hence higher number of these cells in the circulation is associated with more aggressive thyroid cancer." (PMID 38235146, 2023). "The fraction of memory B cells, naive B cells, activated dendritic cells, resting dendritic cells, M1 macrophages, monocytes, plasma cells, activated memory CD4 T cells, and regulatory T cells (Tregs) were significantly different in the four tumor stages of thyroid carcinoma of the different groups." (PMID 34141614, 2021). "Our analysis also uncovered that BRAF V600E mutation in thyroid cancer (THCA) creates an immune suppressive tumor microenvironment by increasing Treg, neutrophil, and monocyte infiltration, while decreasing the infiltration of NK cells and CD4+ T-cells." (PMID 30622534, 2018).
thyroid cancer (continued). "As described in some of our studies, CD4+ and CD8+ T cells were significantly affected by the presence of DN T cells in thyroid cancer TIME." (PMID 40075642, 2025). "A similar result was obtained for thyroid cancer, where TRPA1 is highly expressed only in infiltrated B cells, CD4+ T cells and dendritic cells and is correlated with better overall survival." (PMID 39770499, 2024). "Many studies have confirmed the high expression of CD4+ T cells, CD8+ T cells, and CD69 in patients with thyroid cancer such as MTC, which indicates obvious T cell reaction in thyroid cancer patients." (PMID 33414407, 2021). "In peripheral blood mononuclear cell of thyroid cancer patients, Pep3 treatment alters percentages of CD8+ and CD4+ T regulatory and CD8+ and CD4+ T effector cells and favors an anticancer immune response." (PMID 34539667, 2021). "Furthermore, we compared the immune infiltration in patients with early versus late thyroid cancer and found that the expression levels of T cells CD8, plasma cells, and CD4 + memory-activated immune cells were significantly different (p< 0.01)." (PMID 37854594, 2023). "Finally, thyroid carcinoma (THCA) showed significance in its Tgammadelta (p = 0.7752), CD4+ (p = 0.4649), and NK (p = 0.0512) cell populations compared to BCC." (PMID 36612301, 2023). "CD4 T-cell population was found in similar proportion in thyroid cancer as in HT, but the subtype distribution does not seem to be the same." (PMID 35692772, 2022). "previously identified a new subset of B cells expressing PD-1 that could inhibit the functions of CD4+ T cells and CD8+ T cells in differentiated thyroid cancer." (PMID 35935985, 2022). "Interestingly, H19 in thyroid cancer positively correlated with CD8+ T cells, CD4+ T cells, B cells, and other infiltrates, which indicates that in some contexts, lncRNA-miRNA interactions may increase the recruitment of immune cells." (PMID 41154428, 2025). "In addition, we observed a significant correlation between the expression of AIF-1 and various types of infiltrating immune cells, including CD8+ T cells, CD4+ T cells, B cells, macrophages, NK cells, and dendritic cells in both thymic carcinoma (THYM) and thyroid carcinoma (THCA)." (PMID 37014322, 2023). "Our research findings strongly demonstrate that many immune properties against thyroid cancer exist in Treg, such as CD28‐ DN (CD4‐ CD8‐) %DN, CD3 on activated and secreting Treg, CD3 on CD28+ CD4+, CD28 on CD39+ CD4+, CD127 on CD45RA‐ CD4 not Treg and CD4 on secreting Treg." (PMID 41189243, 2025).